ENSG00000212347
Synonyms: LOC124900502
Gene: Small nucleolar RNA gene on chromosome X (45,892,912 to 45,892,979, reverse strand). Ensembl gene ENSG00000212347.
Gene Ontology:
Biological process: RNA processing
Cellular component: nucleolus
Homologues: Orthologues: zebrafish snord80.1 (59% identical), zebrafish snord80.2 (59% identical). Paralogues in human: SNORD77B (87% identical).